TNF (tumor necrosis factor)
Diseases named in the same sentence as TNF in open-access papers (continued):
Sharing a sentence is not in itself a finding about the gene and the disease.
Kawasaki disease (38 papers, 2009 to 2026). A rare inflammatory disease characterized by an acute febrile, systemic, self-limiting, medium-vessel vasculitis primarily affecting children. "For example, in Kawasaki disease, TNF-α induces vascular endothelial cell apoptosis by causing the overexpression of pregnancy-induced non-coding RNA49." (PMID 27958323, 2016). "Tumor necrosis factor (TNF)-α is elevated during the acute phase of Kawasaki disease (KD), which damages vascular endothelial cells to cause systemic vasculitis." (PMID 25007068, 2014). "It is for example known that anti-TNF works beneficial in animal models for Kawasaki disease associated coronary aneurysms." (PMID 19582157, 2009). "In our previous research we have found that patients with Kawasaki disease had higher levels both M1 related cytokine TNF-α, and the M2 related cytokines IL-6, IL-4 and IL-13 in the acute phase of Kawasaki disease, which decreased after IVIG therapy." (PMID 35154107, 2022). "Studies have been shown that tumor necrosis factor (TNF) and TNF receptor family members are abnormally expressed in the acute phase of Kawasaki disease, also revealing that these two play a significant role in the pathogenesis of KD." (PMID 34484292, 2021). "The lincRNA THRIL, whose expression levels correlated with the severity of Kawasaki disease, induced expression of TNF-α by forming a ribonucleoprotein (RNP) complex with hnRNPL." (PMID 32929606, 2020). "Elevated interleukin-1β (IL-1 β) and tumor necrosis factor-α (TNF- α) have beenidentified at the BCG scar in patients with Kawasaki disease." (PMID 31859956, 2019). "Enzyme-linked immunosorbent (ELISA) was used to detect serum levels of chemerin, omentin-1, adiponectin, and inflammatory cytokines IL-1β and TNF-α in 80 cases of patients diagnosed with Kawasaki disease (KD)." (PMID 29739418, 2018). "Infliximab, which is a neutralizing TNF inhibitor, has recently attracted attention as a therapy for Kawasaki disease (KD)." (PMID 25317081, 2014). "The mainstay of treatment for Kawasaki disease is aspirin and intravenous immunoglobulins (IVIG), but recent studies have demonstrated the efficacy of corticosteroids plus IVIG and anti-tumor necrosis factor alpha (TNF-α) drugs in managing IVIG-resistant Kawasaki disease." (PMID 36185934, 2022). "THRIL is an immunoregulatory lncRNA that was shown to regulate the expression of pro-inflammatory cytokine TNF-α in Kawasaki disease and other immune-related inflammatory diseases through interacting with hnRNPL forming an RNA—protein complex to bind TNF-α promoter." (PMID 34885054, 2021). "Our data are also consistent with in vivo observations wherein IVIg treatment reduces serum IL-6 and IL-6 production by LPS-stimulated whole blood in children with Kawasaki disease, and reduces serum TNF and IL-1β levels in patients with Guillain-Barré syndrome." (PMID 30515163, 2018). "TNF-α is a pleiotropic inflammatory cytokine elevated during the acute phase of Kawasaki disease." (PMID 25431574, 2014). "The early event of immune response in Kawasaki disease is the activation of innate immune system, with elevated numbers of activated neutrophils and monocytes as well as increased expression of circulating cytokines [interleukin (IL)-1, IL-6, and tumor necrosis factor (TNF)] signaling pathways." (PMID 32276581, 2020). "T cells further recruit immune cells to the vessel wall by secreting cytokines such as IL-1β, TNF-α and chemokines such as CCL2.In animal models, CD8+ T cells are essential for the development of vascular inflammation in Kawasaki disease." (PMID 40746545, 2025). "In Kawasaki disease, similarly to TAK, the inflammatory process is complex, and IL-6, IL-8, TNF-α, IFN-γ, and CRP are involved in the course of the disease." (PMID 37626704, 2023). "The KDSS in acute phase of Kawasaki disease is IVIG-resistant with higher level of inflammatory cytokines such as IL6, TNFα, and IL1 and good response to methylprednisolone pulses." (PMID 36585531, 2022).
Kawasaki disease (continued). "On the other hand, IL-35 dampened TNF-α and granzyme B production by CD14+ monocytes in Kawasaki disease, however, only granzyme B contributed to the cytotoxicity of CD14+ monocytes." (PMID 32276581, 2020). "IL-35 also inhibited tumor necrosis factor-α and granzyme B secretion by CD14+ monocytes from patients with Kawasaki disease, however, only granzyme B was responsible for the cytotoxicity of CD14+ monocytes." (PMID 32276581, 2020). "In 17 patients with Kawasaki disease, linc1992/THRIL expression was lower during acute phase of disease when TNFα levels are elevated, so linc1992/THRIL could be a new biomarker for immune activation." (PMID 25431574, 2014). "The increase of PCT in monocytes and granulocytes mediated by the activated innate immune system after KD onset through tumor necrosis factor (TNF) signaling pathways could lead to impairing of endothelial cell, which may relate to the etiology of Kawasaki disease." (PMID 34530763, 2021). "Nine to 23% of Kawasaki disease patients are not responsive to IVIg therapy and up to 40% of IBD patients are, or will become, refractory to anti-TNFα therapy, approximately half of whom have not developed anti-drug antibodies." (PMID 30515163, 2018).
metastatic disease (38 papers, 2002 to 2025). "When broken down by individual T, N, and M categories, median TNF-α values were highest in T4 and M1 lesions, suggesting that extensive local invasion and metastatic disease are associated with elevated TNF-α." (PMID 40299527, 2025). "In PCa, high levels of TNF-α are associated with increased tumor cell migration and metastatic disease." (PMID 40427694, 2025). "When measuring associations with metastatic disease at presentation, TNF antagonist use trended towards an association with reduced metastases at diagnosis, but this was not statistically significant (OR: 0.581, p = 0.108)." (PMID 36371231, 2022). "Increased TNF-α blood levels are observed in cancer patients and are correlated with an increased risk of metastatic diseases." (PMID 33925516, 2021). "Thus, the decrease of FOSB in metastatic disease may cause divergence between TNFα and IL-6 PCa expression levels by changing the available ratios of the corresponding translated proteins for dimerization." (PMID 36371231, 2022). "Hypercalcemia in metastatic disease is mediated through various factors, such as parathyroid hormone-related protein (PTHrP), interleukin-1 (IL-1), IL-6, tumor necrosis factor-alpha (TNF-α), and colony-stimulating factors (CSFs)." (PMID 40149349, 2025). "We analyzed somatic tumor RNA-seq data for expression levels of TNFα and IL-6 in localized versus metastatic disease." (PMID 36371231, 2022). "We observed statistically significant opposing patterns of IL-6 and TNFα expression between localized and metastatic disease." (PMID 36371231, 2022). "The results showed that the protein levels of IL-1b and TNF-a in the hepatocyte co-culture+IL-6 treated LUADs derived metastatic tumor were dramatically elevated, whereas significantly decreased in the hepatocyte co-culture+Peptide 17 treated LUADs." (PMID 33495421, 2021). "TNFα is also expressed by Ewing’s sarcoma primary tumors at higher levels than the metastatic disease." (PMID 34327193, 2021). "For all cases, including macrophage only, or with either primary or metastatic tumor cells, the TNF-α level was 5× higher with the M1 activated group than with the M2 group." (PMID 31636296, 2019). "Accordingly, the production of TNF-α was set in the simulations for the metastatic tumors to be 10× higher than for the primary tumors, which used the baseline value in18." (PMID 31636296, 2019). "Here, we suggest that two cytokines are responsible for the regulation of epithelial plasticity of cancer cells in primary and metastatic tumors: TNFα is responsible for inducing EMT in primary tumors, whereas IL-35 promotes MET in metastatic tumors." (PMID 30218063, 2018). "Significantly higher levels of the pro-osteoclastogenic cytokines IL-17F,RANKL, IL-1β, TNFα, and IL-6 were detected in the sera and supernatants fromLN-stimulated cells of animals bearing the metastatic tumors than in mice withnon-metastatic tumors." (PMID 23935856, 2013). "The results of our study showed the highest level of TNF α in patients with malignant tumors (primary adrenocortical carcinoma and metastatic tumors)." (PMID 20640152, 2010). "Significantly elevated levels of TNF-α were found in metastatic disease (6.3±3.6 pg ml−1) compared with localised disease (1.1±0.5 pg ml−1, P<0.001)." (PMID 15150588, 2004). "Blocking the TNF-α-mediated survival pathway by adalimumab may be an effective therapy for SCEL-positive TNBC patients with pulmonary metastatic disease." (PMID 38037106, 2023). "Notably, with progression to metastatic disease there are decreases in estrogen response signaling and TNF signaling via NF Kappa B (NFKB) (denoted in blue)." (PMID 37704753, 2023). "Additionally, oxygen-free radicals and ionizing radiation have been shown to stimulate SOD2 expression in a TNFα-dependent manner, as altered TNFα levels correlate with enhanced metastatic disease." (PMID 35164076, 2022).
metastatic disease (continued). "This discrepancy may suggest that TNFα promotes metastatic disease through signaling that is distinct from the classical pro-inflammatory pathways triggered by this cytokine." (PMID 36371231, 2022). "Thus, 4T07 primary tumors prime systemic CD8+ T cells that induce cell cycle arrest of DCCs by IFNγ and TNFα and thereby prevent overt metastatic disease." (PMID 33536445, 2021). "Moreover, we evaluated the protein level of two inflammatory cytokines (IL-1b and TNF-a) in the metastatic tumors." (PMID 33495421, 2021). "The first is the capacity of Everolimus to restrain the progression of skeletal metastatic disease in BC patients through a specific mechanism that includes inhibiting the release by these cells of the most effective pro-OC factors such as M-CSF, TNFα, IL-1β, IL-6, MIP-1α and MMP-13." (PMID 26468083, 2015). "However, knockdown of either OTUD1 or FGL1 in MC38 cells reduced hepatic metastases, which could be rescued by overexpressing rFGL1, indicating the critical role of FGL1 in TNFα-mediated progression of metastatic tumors." (PMID 37872170, 2023). "Furthermore, KSG-002 can be applied in different cancer cell types that are highly metastatic, as TNFα may be plentiful in metastatic tumor cohorts." (PMID 23818931, 2013). "We examined the upstream transcriptional factors (TFs) associated with TNFα and IL-6 regulation such as the Activator Protein 1 (AP-1) family of TF’s, NFkB and CEBP to decipher molecular mechanisms that may drive the differential expression of these cytokines in localized versus metastatic disease." (PMID 36371231, 2022). "Of note, most of the organoids derived from metastatic tumors show resistance to palbociclib (CDK4/6 inhibitor) and cepharanthine (inhibiting TNF‐α‐mediated NFκB stimulation)." (PMID 34605222, 2021). "Similar toxicity was observed when tumor necrosis factor-alpha (TNF-α) in combination with radiation was tested for locally advanced and metastatic tumors." (PMID 25506582, 2014). "Cells from the metastatic tumor 147L lacked RIPK3 expression, yet SM-164 sensitized these cells to TNFα as efficiently as cells from the RIPK3-expressing tumors 493L and 1029LV." (PMID 27129149, 2016).
prostatitis (38 papers, 2008 to 2025). An infectious or non-infectious inflammatory process affecting the prostate gland. "Prednisolone downregulates key pro‐inflammatory cytokines such as TNF‐α, IL‐1β, and IL‐6, which are implicated in the pathogenesis of both UC and chronic prostatitis." (PMID 40909304, 2025). "Elevated levels of pro-inflammatory cytokines—principally interleukin (IL)-1, IL-6, and tumor necrosis factor-alpha (TNF-α)—have also been observed in prostatic fluids of chronic prostatitis patients and are associated with inflammatory conditions." (PMID 40607213, 2025). "Further research, including considerable sample sizes, will be required in the future to elucidate the function of the TNF-α-308G/A and TNF-α-238G/A polymorphisms in prostate carcinogenesis." (PMID 38745115, 2024). "Our results indicate that, in comparison to the prostatitis group, the expression levels of the proinflammatory factors TNF-α and IFN-γ exhibited varying degrees of reduction following treatment with RTX at different dosages." (PMID 40070569, 2025). "Increasing reports have demonstrated that suppressing the production of pro-inflammatory cytokines, such as IL-1β, IL-6, and TNF-α, can reduce the effect of prostatitis." (PMID 39291282, 2024). "Inflammatory cytokines, particularly TNF-α and IL-10, are elevated in prostatitis, and their presence has been detected in the urine of prostatitis patients." (PMID 38258089, 2024). "C57BL/6 mice received 5 mg/kg body weight of 1-adrenergic or 2-adrenergic receptor agonists intraperitoneally for five days and developed chronic prostatitis, characterized by increased pro-inflammatory cytokines TNF, IL-6, and chemokines CCL2, CCL3." (PMID 37228599, 2023). "In general, tests for IL-1, IL-6, IL-8 and TNF-α expression levels can be an indicator to verify the success of prostatitis." (PMID 37228599, 2023). "Interleukin‐6 (IL‐6), interleukin‐8 (IL‐8), tumor‐necrosis factor‐α (TNFα), and interleukin‐1β (IL1β) are among the main cytokines that correlate with leukocytospermia and chronic prostatitis or chronic pelvic pain syndrome (CP/CPPS)." (PMID 33794059, 2021). "Ingenuity Pathway analysis showed crosstalk of RASAL2 and several genes including TNFα which is an important signaling intermediate in prostate carcinogenesis." (PMID 34966481, 2021). "In our study, it appears that there is a crosstalk between RASAL2 and TNFα signals in prostate carcinogenesis." (PMID 34966481, 2021). "IL-1β and TNF-α are both pro-inflammatory cytokines and reported to be up-regulated in prostatic sections of prostatitis, suggesting that these are the key markers in inflammatory prostate." (PMID 31646996, 2019). "Previous reports have found that the levels of some molecules associated with pain conditions, including CCL3, IL-1B, TNF-α, brain-derived neurotrophic factor (BDNF), and substance P, are increased in the spinal cord of prostatitis animal models." (PMID 31653262, 2019). "Khalili M etal found a significant decrease in AR expression in infected prostate glands by preparing a bacterial prostatitis model, and very low TNF-α and IL-1β exposure can also lead to inhibition of the androgen receptor pathway." (PMID 31372097, 2019). "Seminal plasma from patients with chronic prostatitis (CP)/chronic pelvic pain syndrome show significantly higher levels of TNF-α and IL-1β when compared with those from healthy subjects, while no involvement of IFN-γ has been reported." (PMID 29896191, 2018). "Therefore, the measurement of cytokine expression, particularly IL-1, IL-6, IL-8 and TNF-α, provides a reliable indicator of the success of the prostatitis model." (PMID 37228599, 2023). "Furthermore, in a murine model of prostatitis, prostate-specific autoantibodies as well as NO, TNF-α, and IFN-γ in seminal plasma were elevated." (PMID 28386549, 2017). "However, to clarify the role of TNF-α-308G/A and TNF-α-238G/A polymorphism in prostate carcinogenesis, more studies with large samples are needed in the future." (PMID 24666463, 2014).
prostatitis (continued). "Of the seven TNF-up-regulated genes identified, PTGS2 (COX-2) is involved in inflammation-mediated oxidative stress favoring prostatic carcinogenesis." (PMID 18560533, 2008). "Our results reveal that PARP1 aggravated prostatitis, and promoted macrophage and neutrophil infiltration at inflammatory sites and upregulates the expression of inflammatory cytokines such as IL-6, CCL2, and TNF." (PMID 40032778, 2025). "Research revealed that their metabolic products may be involved in the reduction of the inflammatory factor TNF-α and its membrane receptor TNF-R2, which may be related to the protective capacity of the phylum Verrucomicrobia against prostatitis." (PMID 38680919, 2024). "It is reported that total glucosides of V. officinalis attenuate chronic nonbacterial prostatitis in rat models by reducing the release of IL-2, IL-1β, and TNF-α in the prostate." (PMID 37108306, 2023). "The study demonstrated that the flavonoids and polysaccharides of T. patula could alleviate prostatitis by improving the level of DHT, reducing the secretion of PSA and TNF-α." (PMID 31216740, 2019). "Some anti-angiogenesis related genes were essentially down-regulated in PC3 cells, i.e. MMP2, TNF-alpha, CCL11 and the potent pro-angiogenic factor IGF1 (9 fold down-regulation) which is deeply involved in prostate carcinogenesis and identified as autocrine proliferation stimulus for hPCa cells." (PMID 24681516, 2014). "In addition to causing an increase in all of the indices of inflammation in the tissue, the ethanol-DNBS-induced prostatitis resulted in an elevation of the tissue proinflammatory cytokines IL-6, IL-1β, and KC but not TNF-α." (PMID 24459330, 2013). "Additionally, the expression of IL-6, IL-12p70, CCL2 and TNF in the Parp1−/− model group was markedly reduced and IL-10 increased significantly compared to that in the WT model group, suggesting that PARP1 enhanced the inflammatory factors secretion in prostatitis." (PMID 40032778, 2025). "Since increased levels of inflammatory cytokines including IL-1β and TNF-α are also found in prostatitis, with or without bacterial infection, they may also up regulate CFTR in the prostate, thereby enhancing HCO3− secretion and leading to the characteristic pH increase in prostatitis." (PMID 21151921, 2010).